SNORD93 (small nucleolar RNA, C/D box 93)
Synonyms: HBII-336
Gene: Small nucleolar RNA gene on chromosome 7 (22,856,613 to 22,856,686, forward strand). Ensembl gene ENSG00000221740.
Gene Ontology:
Biological process: RNA processing
Cellular component: nucleolus
Homologues: Orthologues: macaque SNORD93 (97% identical), pig SNORD93 (88% identical), rabbit SNORD93 (88% identical), guinea pig SNORD93 (86% identical), mouse Snord93 (86% identical), mouse Gm50451 (85% identical).
Diseases named in the same sentence as SNORD93 in open-access papers:
SNORD93 is named in the same sentence as 2 diseases in open-access papers, as found by Europe PMC text mining. Sharing a sentence is not in itself a finding about the gene and the disease. The quoted sentences say what the papers report.
respiratory diseases (1 paper, 2025). "Previously identified smoking-related CpG sites that were also linked to smoky coal combustion – annotated to genes such as AHRR, SNORD93, NWD1, EDC3, STK24, ZDHHC14, HIF3A – converge on key pathways involved in pollutant response, respiratory diseases, and carcinogenesis." (PMID 40236422, 2025).
tumor (1 paper, 2024). "Overexpression of certain genes promotes metastasis, including the DNAJ3A3 gene from the heat shock protein (HSP) family, which promotes tumor invasion, and the small nucleolar RNA, C/D Box 93 (SNORD93) gene, which blocks the expression of metastasis genes." (PMID 38275618, 2024).